Y_RNA (Y RNA )
Gene: Miscellaneous RNA gene on chromosome 7 (6,004,283 to 6,004,385, reverse strand). Ensembl gene ENSG00000201990.
Homologues: Orthologues: macaque Y_RNA (91% identical), pig Y_RNA (71% identical). Paralogues in human: Y_RNA (89% identical), Y_RNA (88% identical), RNY3 (84% identical), RNY3P1 (83% identical), Y_RNA (83% identical), Y_RNA (82% identical), RNY3P13 (81% identical), RNY3P5 (81% identical), Y_RNA (81% identical), RNY3P14 (80% identical), RNY3P16 (80% identical), Y_RNA (80% identical), and 93 more.